CDC20 (cell division cycle 20)
Diseases named in the same sentence as CDC20 in open-access papers (continued):
Sharing a sentence is not in itself a finding about the gene and the disease.
microcephaly (1 paper, 2020). A congenital or acquired developmental disorder in which the circumference of the head is smaller than normal for the person's age and sex. "Because the biallelic defect of CENPT causes a syndrome characterized by severe growth failure and microcephaly without chromosome number instabilities, which differed from the patient's phenotypes, we further investigated the CDC20 variant in this study." (PMID 33094908, 2020).
myelodysplastic syndrome (1 paper, 2018). A clonal hematopoietic disorder characterized by dysplasia and ineffective hematopoiesis in one or more of the hematopoietic cell lines. "Inversely, there is a correlation between age and expression of the checkpoint genes Mad2, Aurora B and Cdc20 in myelodysplastic syndrome (MDS), an characteristic aging-associated dysplasia of the blood-forming system." (PMID 30066086, 2018).
Myocardial fibrosis (1 paper, 2025). "Using Masson, H&E, and IF (Collagen III and α-SMA) staining, we confirmed that CCDC69 overexpression inhibited the extent of DOX-induced myocardial fibrosis and inflammation mediated by CDC20." (PMID 40045239, 2025).
osteoarthritis (1 paper, 2023). A noninflammatory degenerative joint disease occurring chiefly in older persons, characterized by degeneration of the articular cartilage, hypertrophy of bone at the margins and changes in the synovial membrane. "CDC20 is significantly downregulated in the cartilage transcriptome of osteoarthritis mice." (PMID 36980895, 2023).
osteoporosis (1 paper, 2022). A condition of reduced bone mass, with decreased cortical thickness and a decrease in the number and size of the trabeculae of cancellous bone (but normal chemical composition), resulting in increased fracture incidence. "CDC20 regulates both adipogenesis and osteogenesis of BMSCs, and might lead to the development of new therapeutic targets for “fatty bone” and osteoporosis." (PMID 36056439, 2022). "Furthermore, CDC20 might be involved in balancing adipogenesis and osteogenesis in stem cells in tissue engineering and as a therapeutic target in the treatment of osteoporosis." (PMID 36056439, 2022).
pancreatic adenocarcinoma (1 paper, 2018). "It is reported that CDC20 is up-regulated in pancreatic adenocarcinoma cells." (PMID 29596435, 2018).
pancreatitis (1 paper, 2012). Inflammation of the pancreas. "A qRT-PCR analysis confirmed a mean 20-fold higher CDC20 level in PDAC tissue than in normal pancreas and pancreatitis tissue." (PMID 22475564, 2012).
Pca (1 paper, 2023). "Previous findings indicated that oncogenic CDC20 was overexpressed in Pca, and knockdown of CDC20 resulted in inhibition of cell proliferation, migration, and tumor formation, induced cell apoptosis, and increased radiosensitivity in PCa in vitro and in vivo." (PMID 38136586, 2023).
primary immunodeficiency (1 paper, 2022). "In addition, cell cycle, DNA replication, insulin signaling pathway, MTOR signaling pathway, natural killer cell-mediated cytotoxicity, primary immunodeficiency, TGF beta signaling pathway, and WNT signaling pathway might be the main pathways regulated by CDC20." (PMID 35800227, 2022).
prostate neuroendocrine carcinoma (1 paper, 2023). "Interestingly, the highest positive correlation between CDC20 and KMT5A expression was seen in prostate neuroendocrine carcinoma samples (Spearman = 0.68; p < 0.0001; n = 49)." (PMID 37509260, 2023).
prostate tumor (1 paper, 2026). "SETD6 KO GO Group 2 contains genes promoting prostate tumor growth and migration via regulation of ubiquitin transferases, including DCUN1D5, UBE2S, and CDC20." (PMID 41540805, 2026).
serous ovarian cancer (1 paper, 2024). "Additionally, the Kaplan–Meier plot results revealed that increased expression of ATAD2, CCNE1, CDC20, and SMC4 was associated with poor survival in serous ovarian cancer patients (p < 0.05)." (PMID 39199556, 2024).
squamous carcinomas (1 paper, 2025). "Other key genes, such as CDC20, CCNB1, CHK1, and UBE2C, are well-known regulators of mitotic progression and therapeutic resistance in squamous carcinomas." (PMID 41323280, 2025).
tongue cancer (1 paper, 2021). A malignant neoplasm affecting the tongue. "Tongue cancer patients with high expression of CDC20 demonstrated a worse prognosis, and CDC20 inhibitors were thought to be promising strategies for cancers." (PMID 34440557, 2021).
urothelial carcinoma (1 paper, 2020). A malignant neoplasm derived from the transitional epithelium of the urinary tract (urinary bladder, ureter, urethra, or renal pelvis). "By contrast, urothelial carcinomas subtypes with a poor prognosis display high expression of late cell cycle genes, including CDK1/cyclin B complex and its activators such as CDC25 family genes, and genes related to chromosome segregation and cell division such as BUB1, CDC20, and CENP." (PMID 31709755, 2020).
Wilms tumor (1 paper, 2021). An embryonal neoplasm characterized by the presence of epithelial, mesenchymal, and blastema components. "The results indicated that the protein level of CDC20 in Wilms tumor tissues was much higher than that in matched nontumor tissues." (PMID 34513754, 2021).
cancer (269 papers, 2008 to 2026). A tumor composed of atypical neoplastic, often pleomorphic cells that invade other tissues. "Dysregulation of APC/C: Cdc20 can lead to genomic instability and is implicated in various diseases, including cancer." (PMID 40565031, 2025). "Overall, the human cancer cell line data suggest that elevated levels of CDC20 expression are associated with increased sensitivity to both genetic and chemical disruption of the SAC." (PMID 39838194, 2025). "CDC20, a cell cycle regulator promoting mitosis, is frequently overexpressed in cancers and associated with poor prognosis." (PMID 40227503, 2025). "CDC20 overexpression was strongly associated with various cancer diseases, like colorectal and breast." (PMID 39908244, 2025). "The upregulated level of CDC20 is linked to cancer initiation, progression, and metastasis, as well as aggressive behavior and chemotherapy resistance in BC, particularly the TNBC subtype." (PMID 39061186, 2024). "Aberrant expression or mutations of CDC20 are associated with cell cycle dysregulation and the development of cancer." (PMID 39518808, 2024). "We identified several proteins with high interaction scores (Cna2, Kif20a, Kif11, Cdk1, and Cdc20) that are closely associated with various cancers." (PMID 39596644, 2024). "Elevated CDC20 expression has been linked to clinicopathological features in various types of human cancers." (PMID 37383715, 2023). "Abnormal expression of CDC20 is commonly associated with malignant progression and poor prognosis in various types of cancer." (PMID 37587140, 2023). "Statistical analysis of clinical trials by many researchers provides evidence of the association between high expression of Cdc20 and cancer patients." (PMID 37259447, 2023). "Aberrant CDC20 overexpression has previously been implicated in pan-cancer disease progression and poor patient prognosis." (PMID 35948941, 2022). "Previous studies showed the role of CDC20 in cancer development and linked its function to drug resistance." (PMID 35954396, 2022). "High expression of CDC20 is a poor prognosis marker and is associated with cancer progression, metastasis, and resistance to therapy." (PMID 35954396, 2022). "In support of the oncogenic role, genetic ablation of CDC20 results in efficient tumor regression, while the loss of CDC20 inhibition promotes tumorigenesis, advocating CDC20 as a potential therapeutic target for cancer treatment." (PMID 33130827, 2021). "For most cancer types, the CDC20 expression was positively correlated with the infiltration of cancer-associated fibroblasts and myeloid-derived suppressor cells." (PMID 34527589, 2021). "Cell division cycle protein (CDC20) has been observed to be expressed higher in various kinds of human cancers and was associated with poor prognosis." (PMID 32285914, 2020). "In conclusion, two multiple cancer-associated genes including CDC20 and CDCA8 were identified as candidate diagnostic biomarkers for BC by analyzing GEO, Oncomine, GTEx, THPA and TCGA data." (PMID 32677673, 2020). "Pathway analysis revealed that SPP1 overexpression affected the expression levels of BRCA1 and CDC20, which have been reported to be associated with several cancers types." (PMID 30517191, 2018). "While CDC20 has been linked to cancer progression, the second APC co-activator, CDH1, has been linked to tumor suppression, with earlier work demonstrating that cells lacking CDH1 have a shortened G1 phase, accumulate DNA damage, and undergo apoptosis." (PMID 29954095, 2018).
cancer (continued). "Knockdown of Cdc20 in various cancer cell lines caused mitotic arrest, cell death and increased sensitivity to chemotherapeutics and radiation." (PMID 26716651, 2016). "Overexpression of Cdc20 has been identified in a broad spectrum of human cancers and is associated with poor prognosis in various types of cancers." (PMID 27626499, 2016). "However, the abnormal expression and mutations of CDC20 are closely related to human diseases, extensively studied in the field of cancer, where it has been identified as a new therapeutic target for cancer treatment." (PMID 39518808, 2024). "Abnormal overexpression of CDC20 can lead to mitotic defects, the main cause of cancer development." (PMID 39061186, 2024). "CDC20, an activator of the anaphase-promoting complex/cyclosome, regulates the transition from metaphase to anaphase, and its aberrant expression is linked to various cancers." (PMID 39201599, 2024). "Conversely, the loss of spindle assembly checkpoint regulation by CDC20 promotes tumorigenic progression, suggesting that CDC20 may be a potential cancer treatment target." (PMID 39114311, 2024). "The gene CDC20 has been implicated in various diseases, including cancer." (PMID 39061186, 2024). "In addition, the overexpression of CDC20 is associated with progression, treatment resistance, poor prognosis, and clinicopathological features in multiple human cancers." (PMID 37682144, 2023). "Additionally, CYP1B1 depletion was shown to reduce the growth, invasion, and migration of cancer cells through the upregulation of cell division cycle 20 homolog (CDC20) and down-regulation of death-associated protein kinase-1 (DAPK1)." (PMID 38001897, 2023). "Recently, CDC20 expression has been also associated with immune infiltration in cancer." (PMID 35490245, 2022). "Moreover, CDC20 expression level has been reported as a putative marker of clinical outcome in many cancer types, being associated with advanced stage, high grade and poor prognosis." (PMID 35490245, 2022). "In addition, we identified novel promoter mutation hotspots in CDC20, which is a known cancer-related gene." (PMID 33851100, 2021). "This implies a function of these CDC20 promoter mutation hotspots in cancer progression." (PMID 33851100, 2021). "In addition, deregulation of APC/C (a representative E3 ligase) together with its co-activators cell division cycle 20 (CDC20) or CDC20-like protein 1 (CDH1) has been associated with cancers." (PMID 34925455, 2021). "Thus, the promoter hotspot mutations reported here can promote cancer progression by up-regulating the transcription of CDC20." (PMID 33851100, 2021). "CDC20 is associated with malignant progression and poor prognosis among various cancers." (PMID 34149795, 2021). "Abnormal CDC20 expression has been detected in most human cancers, and CDC20 knockdown caused mitotic arrest to efficiently kill slippage-prone and apoptosis-resistant cancer cells, supporting an oncogenic role of CDC20." (PMID 31886176, 2019). "Furthermore, CDC20 mRNA expression is observed to be elevated in cancer cells, which is associated with a poor prognosis; CDC20 knockdown is required for mitotic arrest and inhibition of cell growth." (PMID 29954095, 2018). "CDC20 dysfunction can cause prolonged mitotic arrest and apoptosis in cells, which suggests it could be a therapeutic target in cancer research." (PMID 29245942, 2017). "CDC20 could be a novel biomarker for predicting immunotherapy outcomes and immune landscapes in patients and may be an immune-associated therapeutic target in cancers." (PMID 37682144, 2023). "Many studies have suggested that dysregulation of CDC20 is associated with various pathological processes in malignant solid tumors, including tumorigenesis, progression, chemoradiotherapy resistance, and poor prognosis, providing a biomarker for cancer diagnosis and prognosis." (PMID 37682144, 2023).
cancer (continued). "Similarly to other SAC genes, CDC20 is rarely mutated across cancers." (PMID 35490245, 2022). "In addition, recurrent noncoding mutation hotspots were identified in CDC20 gene promoter; these mutations lead to increased transcription of CDC20, which is known to be up-regulated in various cancers and might directly stimulate cancer progression." (PMID 33851100, 2021). "Previous studies have demonstrated that knockdown of CDC20 expression could lead to decreased cellular proliferation in tumor cells, and its overexpression is associated with poor prognosis in many human cancers." (PMID 26626260, 2015). "Genetic ablation of CDC20 leads to efficient tumor regression both in vitro and in vivo, making it an attractive target for cancer therapy." (PMID 40521202, 2025). "High CDC20 expression promotes aneuploid cancer cell sensitivity to spindle assembly checkpoint (SAC) inhibition by shortening metaphase and increasing mitotic errors." (PMID 39838194, 2025). "CDC20 is an E3 ubiquitin ligase that plays a role in cell cycle progression and apoptosis in various types of cancers." (PMID 40045239, 2025). "Among the genes closely related to SPSB2 expression, CDC45, RAD51, TRIP13, MYBL2, and CDC20 play essential roles in cancer development." (PMID 40149497, 2025). "Owing to ongoing advancements in clinical molecular biology, CDC20 has been identified as a crucial contributor to the initiation and progression of malignant tumors, primarily because of its elevated expression levels." (PMID 40045239, 2025). "Similar to our observations in the mouse cells, CDC20 depletion using either shRNA or siRNA led to a substantial decrease in the cellular sensitivity of human cancer cells to SAC inhibition." (PMID 39838194, 2025). "It was found that depletion of endogenous CDC20 in different cancer cell lines induced mitotic arrest and subsequent cell death and effectively inhibited tumor growth by CDC20 ablation." (PMID 41374402, 2025). "Patients with higher expression levels of CDC20 exhibit shorter overall survival, indicating that the expression of CDC20 is an independent prognostic factor for many types of cancer." (PMID 40439120, 2025). "Numerous studies have indicated that CDC20 is not only a potential effective target for various cancer therapies but also a potential biomarker for prognosis." (PMID 40256740, 2025). "High CDC20 expression promotes aneuploid cancer cell sensitivity to spindle assembly checkpoint (SAC) inhibition by prolonging metaphase and reducing mitotic errors." (PMID 39838194, 2025). "CDC20 is a highly conserved and essential regulator of the cell cycle and is considered a promising therapeutic target for various types of cancer." (PMID 40439120, 2025). "WDR77 was predominantly expressed in malignant cells across pan-cancer datasets and positively correlated with CDC20." (PMID 41425556, 2025). "CDC20 is a highly conserved and essential regulator of the cell cycle and is considered a promising therapeutic target in various types of cancer." (PMID 40439120, 2025). "Numerous studies have demonstrated that CDC20 is highly expressed in various malignant tumors, suggesting its involvement in tumor occurrence and progression." (PMID 40045239, 2025). "Lastly, the decreased expression of cell division control 20 (Cdc20) and separins genes would lead to the arrest in the M checkpoint, being catastrophic for cancer cells." (PMID 38674023, 2024). "This study investigated and enhanced our understanding of the molecular mechanisms underlying CDC20’s role in cell cycle control and DDR, thereby reinforcing its potential as a promising therapeutic target for malignant tumors." (PMID 39125953, 2024). "The CDC20 expression level in BC exhibited a significant positive link (p = 1.79 × 10−04) to tumor purity, the ratio of cancer cells in a sample." (PMID 39061186, 2024).